CX3CL1 (C-X3-C motif chemokine ligand 1)
Diseases named in the same sentence as CX3CL1 in open-access papers (continued):
Sharing a sentence is not in itself a finding about the gene and the disease.
viral infection (6 papers, 2017 to 2025). "Expression of CX3CL1/CX3CR1 in viral infection and associated diseases." (PMID 38674036, 2024). "In the following sections, we reviewed the literature on the changes in CX3CL1 during viral infection and its role in the disease." (PMID 38674036, 2024). "Recently, there has been a growing interest in the role of CX3CL1 in regulating cell adhesion, chemotaxis, and host immune response in viral infection." (PMID 38674036, 2024). "It is worth noting that CX3CL1 is a critical element in the development of virus infection and related diseases, facilitating the migration of immune cells to distant organs." (PMID 38674036, 2024). "CX3CL1 expression can be increased by inflammatory cytokines present during viral infections and, in cardiovascular disease, this chemokine increase in the vasculature leads to recruitment of CX3CR1+ T cells." (PMID 33653907, 2021). "CX3CL1 is a cell surface-expressed chemokine and plays a distinct role in several aspects of leukocyte activation and motion during inflammation and viral infection." (PMID 28903751, 2017). "In short, viral infection is related to the expression of CX3CL1." (PMID 38674036, 2024). "Membrane-bound CX3CL1, expressed by endothelial cells, may serve as adhesion molecule promoting intercellular interaction and endothelial cell injury in diseases including in viral infection." (PMID 40384979, 2025).
amyloid (5 papers, 2019 to 2025). "AD-induced amyloidosis causes release of fractalkine (CX3CL1) from neurons, which by stimulating its receptor CX3CR1 that is present on microglia and several leukocyte types, promotes neural and vascular inflammation and reduced eNOS and nitric oxide (NO)." (PMID 30519973, 2019). "In the SMC-calc vs. SMC comparison based on limma, clusters related to high-density lipoprotein (HDL) assembly (PF4V1, APOA1, LPXN, AFP, A2M, and MMP1) and amyloidosis (CX3CL1, APOE, PLIN3, TGFBI, and CH25H) were identified." (PMID 41301179, 2025). "For example, it has been reported that, similar to CX3CR1 deficiency, amyloid precursor protein/presenilin-1 (APP/PS1) mice lacking CX3CL1 showed reduced amyloid pathology, and expression of obligate sFKN in this context did not improve or exacerbate this effect." (PMID 32410624, 2020).
endothelial dysfunction (5 papers, 2009 to 2022). In vascular diseases, endothelial dysfunction is a systemic pathological state of the endothelium (the inner lining of blood vessels) and can be broadly defined as an imbalance between vasodilating and vasoconstricting substances produced by (or acting on) the endothelium. "CX3CL1, also known as fractalkine (FKN), is highly expressed by activated endothelial cells and is known to be involved in endothelial dysfunction, contributing to the development of atherosclerosis and other cardiovascular events." (PMID 35464491, 2022). "Here we propose a model in which CX3CR1+ CD8 T cells promote endothelial dysfunction by the combined effects of CX3CL1, IL-15, and TNF." (PMID 32976527, 2020). "Inhibiting Src/P115-RhoGEF/ROCK signaling in VMECs effectively blocked CX3CL1-induced vertebral vascular endothelial dysfunction and subsequent tumor cell TEM." (PMID 32390803, 2020). "Endothelial dysfunction biomarkers including von Willebrand factor, VCAM-1 and thrombomodulin, as well as the soluble form of CX3CL1 were measured by enzyme-linked immunosorbent assays (ELISA)." (PMID 19587779, 2009). "We explored these polymorphisms in a case-control study and evaluated endothelial dysfunction by measuring several biomarkers including VWF, VCAM-1 and thrombomodulin, as well as the soluble form of CX3CL1." (PMID 19587779, 2009). "Supporting our model, we demonstrate increased expression of CX3CL1 and IL-15 in human atherosclerotic plaques and in the aortic endothelium of SIV/SHIV-infected RM, reflecting microenvironments that sustain endothelial dysfunction." (PMID 32976527, 2020).
kidney damage (5 papers, 2019 to 2024).
lung squamous cell carcinoma (5 papers, 2021 to 2025). "Using immunofluorescence, we evaluated the expression of CX3CL1 in histological specimens of neoplastic lung tissue from squamous cell lung cancer patients." (PMID 41210693, 2025). "The pattern of CX3CL1 expression found in squamous cell lung cancer tissues could have important clinicopathological applications and biological implications in the pathophysiology of this type of cancer." (PMID 41210693, 2025). "The frequent absence of positive immunoreactivity for CX3CL1 in the nucleus of squamous cell lung cancer cells could be part of a differential local transcriptomic fingerprint and may be related to the transformation processes in this type of cancer." (PMID 41210693, 2025).
malaria (5 papers, 2016 to 2023). Malaria is a serious and sometimes fatal disease caused by a parasite that commonly infects a certain type of mosquito which feeds on humans. "Increased IFN-γ, IL-4, IL-10, IL-27, CXCL10, and CX3CL1 levels were observed in malaria monoinfection compared to HIV virus monoinfection." (PMID 36716305, 2023). "Increased IFN-γ, CXCL10, CX3CL1, IL-18, and IL-27 levels were observed in malaria coinfections compared to HIV monoinfection." (PMID 36716305, 2023). "They demonstrated that malaria and L. loa co-infections had decreased levels of C-X-C motif chemokine 5 (CXCL5) and comparable levels of CX3CL1, CXCL7, CXCL9, CXCL11, and CCL28 compared with malaria monoinfection." (PMID 36269701, 2022). "This study aimed to investigate whether and how the plasma concentrations of eight soluble bio-molecules, namely Neopterin, sCD163, suPAR, Pentraxin3, sCD14, Fractalkine/CX3CL1, sTREM-1 and MIG/CXCL9, differ among young patients presenting with distinct clinical manifestations of malaria." (PMID 27357958, 2016).
metabolic syndrome (5 papers, 2015 to 2025). A cluster of metabolic risk factors for CARDIOVASCULAR DISEASES and TYPE 2 DIABETES MELLITUS. "We characterized immune cell behavior in metabolic syndrome, its consequences, and the potential involvement of the CX3CL1/CX3CR1 and CCL2/CCR2 chemokine axes." (PMID 31109070, 2019). "Notably, the neutralization of CX3CL1 or CCL2 activity on HUAEC led to a decrease in platelet-leukocyte endothelial adhesion in the metabolic syndrome group only after TNFα stimulation of HUAEC." (PMID 31109070, 2019). "Additionally, CX3CL1/CX3CR1 or CCL2/CCR2 axes are potential candidates for therapeutic intervention in cardiovascular disorders in metabolic syndrome patients, as their blockade impairs the augmented arterial platelet-Mon1 monocyte aggregate adhesiveness, which is a key event in atherogenesis." (PMID 31109070, 2019). "IR has been shown to increase plaque vulnerability by overexpressing the CX3CL1/CX3CR1 axis, which is one of the possible factors linking diabetes or metabolic syndrome with cardiovascular disease." (PMID 41153665, 2025). "The neutralization of either CX3CL1 or CCL2 activity on HUAEC again markedly reduced TNFα-induced leukocyte adhesion in the metabolic syndrome group, but not in the control group." (PMID 31109070, 2019). "A recent cohort study demonstrated that subjects with metabolic syndrome had higher serum CX3CL1 levels at baseline than those without, and that baseline CX3CL1 levels were an independent predictor of development of metabolic syndrome over a 2 year follow-up period." (PMID 26393344, 2015).
osteoporosis (5 papers, 2019 to 2025). A condition of reduced bone mass, with decreased cortical thickness and a decrease in the number and size of the trabeculae of cancellous bone (but normal chemical composition), resulting in increased fracture incidence. "Multiple studies have also shown that CX3CL1 is involved in the progression of osteoporosis, and the imbalance of bone remodeling caused by abnormal osteoclast differentiation is a key factor leading to osteoporosis." (PMID 37626378, 2023). "In addition, CX3CL1 has been recognized as one of the important immunological markers for the evaluation of osteoporosis risk and prognosis." (PMID 38283363, 2023). "Based on their known involvement in osteoporosis, Atp6v0c, Cx3cl1, and Ly6a are the most promising targets of C3G action in osteoblasts." (PMID 36245484, 2022). "Regarding the fact that acting against the CX3CL1/CX3CR1 axis is a potential target of immune treatment in osteoporosis, the number of available papers tackling the topic is certainly insufficient." (PMID 31780870, 2019). "Few studies are available worldwide which tackle the issue of laboratory evaluation of the role of CX3CL1 in the pathophysiology of osteoporosis." (PMID 31780870, 2019). "The obtained results explicitly indicated the correlation between CX3CL1 concentration in blood serum and the degree of osteoporosis development." (PMID 31780870, 2019). "For example, by inhibiting CX3CL1 or its receptor CX3CR1, the formation and activity of osteoclasts can be reduced, thereby slowing bone loss, which is important for the treatment of skeletal diseases such as osteoporosis." (PMID 41416066, 2025). "Administration of anti-CX3CL1 monoclonal antibodies has been shown to suppress the migration and differentiation of osteoclast precursor cells, reduce the number of mature osteoclasts, and markedly alleviate bone loss in ovariectomized (OVX) mouse models of osteoporosis." (PMID 41416066, 2025). "The anti-CX3CL1 mAb group of mice showed a significant increased BMD value, which is the gold standard for diagnosing osteoporosis." (PMID 37626378, 2023). "Cx3cr1 is expressed in osteoclast precursors, implying that CX3CL1/CX3CR1 signaling can regulate osteoclast differentiation and thus affect the development of osteoporosis." (PMID 36245484, 2022). "The experiment may indicate a possible correlation between the CX3CL1/CX3CR1 axis and LPA/LPAR1 in the promotion of osteoclastogenesis processes, at the same time indicating the use of LPA antagonists to be a highly promising direction in the treatment of osteoporosis." (PMID 31780870, 2019).
pancreatic ductal adenocarcinoma (5 papers, 2011 to 2022). An infiltrating adenocarcinoma that arises from the epithelial cells of the pancreas. "NF-κB can affect the infiltration of CD8+ T-cells in pancreatic ductal adenocarcinoma cells by regulating the generation of CXCL16 and CX3CL1 and thereby promoting the apoptosis of pancreatic ductal adenocarcinoma cells." (PMID 33062724, 2020). "Moreover, human pancreatic ductal adenocarcinoma (PDAC) cells express CX3CR1 and CX3CL1 abundantly and the CX3CR1/CX3CL1 axis can regulate intraneural invasion of PDAC." (PMID 24966464, 2014).
Peritoneal Fibrosis (5 papers, 2020 to 2025). Disorder characterized by a wide range of structural changes in PERITONEUM, resulting from fibrogenic or inflammatory processes. "In our NaClO-induced peritoneal fibrosis pig model, we previously reported significant peritoneal fibrosis and overexpression of fibrosis-related factors, such as CX3CL1 and TGFβ on the peritoneum." (PMID 35453560, 2022).
pulmonary hypertension (5 papers, 2017 to 2024). Increased pressure within the pulmonary circulation due to lung or heart disorder. "It was found that higher levels of CX3CL1-CX3CR1 and plasma soluble CX3CL1 in patients with pulmonary hypertension than in the control group and the expression and function of CX3CL1 in circulating T cells were upregulated." (PMID 35186183, 2022).
AIDS (4 papers, 2006 to 2025). A syndrome resulting from the acquired deficiency of cellular immunity caused by the human immunodeficiency virus (HIV). "Interestingly, we also noted that CX3CL1 levels are higher in PWH with AIDS diagnosis before ART initiation." (PMID 40943350, 2025). "Compared to AIDS patients without HAD, the brain tissue of patients with HAD shows an over-expression of CX3C chemokine, fractalkine/CX3CL1." (PMID 16712719, 2006).
dermatomyositis (4 papers, 2012 to 2025). Dermatomyositis (DM) is a type of idiopathic inflammatory myopathy characterized by evocative skin lesions and symmetrical proximal muscle weakness. "Previous studies have defined the role of CX3CL1 in pathogenesis of RA and other chronic diseases such as polymyositis and dermatomyositis." (PMID 24799766, 2014). "In an MDA-5 amyopathic dermatomyositis–ILD patient, adding MMF (1.5 g/day) improved PF ratio and lowered FGF-2, CX3CL1, IL-1ra, IL-17A, IP-10 and MCP-1." (PMID 40650314, 2025). "Similarly to human RA, polymyositis and dermatomyositis are characterized by chronic muscle inflammation with infiltration of CX3CR1+ cytotoxic T cells and macrophages, recruited by CX3CL1 expressing vascular endothelial cells and other inflammatory cells." (PMID 24799766, 2014).
fibrosis (4 papers, 2018 to 2025). the formation of excess fibrous connective tissue in an organ or tissue in a reparative or reactive process. "Overall, the results showed the predictive value of CX3CL1/Fractalkine in terms of fibrosis/cirrhosis development in chronic HBV infection." (PMID 39329945, 2024). "It demonstrated that intravenous administration of T. cruzi-derived neurotrophic factors in MyD88-knockout mice (deficient in TLR signaling) increased CX3CL1 and CCL2 levels, modulating inflammatory responses mediated by Trk signaling and reducing cardiac fibrosis." (PMID 40936920, 2025). "Furthermore, in HBV-infected patients with severe fibrosis/cirrhosis, we observed significantly lower concentrations of CX3CL1/Fractalkine compared to those with no/mild fibrosis." (PMID 39329945, 2024).
myocarditis (4 papers, 2012 to 2022). Myocarditis is a condition that is characterized by inflammation of the heart muscle (myocardium). "Thus, another therapeutical approach of PVB19 myocarditis has recently been discussed targeting chemokine receptor of fractalkine (CX3CL1)." (PMID 22438961, 2012). "Finally, we conclude that the modulation of the CX3CL1/CX3CR1 axis could be a new important target in the treatment of CVB3-induced myocarditis." (PMID 28800592, 2017). "Since CX3CL1 is expressed by CD68 and CD11b monocytes/macrophages and cardiac fibroblasts, the upregulation in LV CX3CL1 expression in CVB3-infected mice can partly be explained by the increase in monocytes/macrophages and cardiac fibroblast presence in myocarditis mice." (PMID 28800592, 2017). "Since the CX3CR1/CX3CL1 system is upregulated in inflammatory cardiomyopathy and has chemotactic properties, we examined the impact of CX3CR1-/- on cardiac chemokine receptor and chemokine expression in CVB3-induced myocarditis." (PMID 28800592, 2017).
oral squamous cell carcinoma (4 papers, 2021 to 2024). "Taken together, we suggested a novel treatment and a prognostic indicator targeting CX3CL1‐induced tumour motility of human oral squamous cell carcinoma." (PMID 37082943, 2023).
periodontitis (4 papers, 2023 to 2025). An acute or chronic inflammatory process that affects the tissues that surround and support the teeth. "This systematic review aimed to investigate the role of the C‐X3‐C motif ligand 1/chemokine receptor 1 C‐X3‐C motif (CX3CL1/CX3CR1) axis in the pathogenesis of periodontitis." (PMID 38415821, 2024). "The significantly elevated levels of CX3CL1 and its receptor in the group with periodontitis, compared to the control group with healthy periodontal conditions, provide more evidence supporting the involvement of CX3CL1 in the development of periodontitis." (PMID 38590803, 2024). "This systematic review aimed to investigate the role of the CX3CL1/CX3CR1 axis in the pathogenesis of periodontitis and RA." (PMID 38415821, 2024). "For the first time, this study compared healthy controls to patients with varying degrees of periodontitis and measured the amounts of protein (CX3CL1) and the receptor (CX3CR1) in their saliva." (PMID 38590803, 2024). "In comparison to the control group, patients with periodontitis had statistically increased salivary concentrations of CX3CL1 and CX3CR1 (P < 0.001)." (PMID 38590803, 2024). "The observational studies on human subjects diagnosed with periodontitis and RA and/or systemically healthy were selected to analyze CX3CL1 and CX3CR1 biomarkers." (PMID 38415821, 2024). "Regarding pharmacological agents targeting the CX3CL1/CX3CR1 axis in the pathogenesis of periodontitis, it has been shown that the therapeutic CX3CR1 antagonist called “F1” was able to inhibit leukocyte recruitment in a murine model of thioglycolate‐induce periodontitis." (PMID 38415821, 2024). "With the subquestion: Could the CX3CL1/CX3CR1 axis be used as a complementary tool to clinical parameters to distinguish between periodontitis and RA and/or systemically healthy subjects?" (PMID 38415821, 2024). "What is the role of the CX3CL1/CX3CR1 axis in subjects with periodontitis?" (PMID 38415821, 2024). "Within the limitations of the present study and despite its promising clinical applications, it is too early to state that the CX3CL1/CX3CR1 axis can be used as a clinical tool to differentiate the condition of subjects with periodontitis and RA from periodontally and systemically healthy subjects." (PMID 38415821, 2024). "Thus far, the CX3CL1/CX3CR1 axis's role in periodontitis is largely unsupported by the literature, with only six published studies." (PMID 38415821, 2024). "Furthermore, our secondary objective was to determine whether the CX3CL1/CX3CR1 axis could be considered a clinical tool complementary to clinical parameters to distinguish between periodontitis and RA and/or systemically healthy subjects." (PMID 38415821, 2024). "Higher CX3CL1 and CX3CR1 chemokine levels were found in subjects with periodontitis and RA compared with periodontal and systemically healthy subjects." (PMID 38415821, 2024). "In serum, CX3CL1 levels were higher in subjects with RA and Stage III/Grade B periodontitis compared to the other groups." (PMID 38415821, 2024). "In relation to PD, it has been shown that levels of fractalkine/CX3CL1, CX3CR1 and IL-1β in FCG are increased in patients with periodontitis compared to periodontally healthy patients." (PMID 36770741, 2023). "It would be premature to assert, however, that the CX3CL1/CX3CR1 axis can be leveraged as a clinical tool to distinguish between the status of patients with RA and periodontitis and that of periodontal and systemically healthy individuals in the lack of clinical data." (PMID 38415821, 2024). "Therefore, this study seeks to assess the correlation between Fractalkine (CX3CL1) and the receptor for it (CX3CR1), as well as the different stages of periodontitis, to differentiate individuals with periodontitis from those who are periodontally healthy." (PMID 38590803, 2024).